IGF1 (insulin like growth factor 1)
Diseases named in the same sentence as IGF1 in open-access papers (continued):
Sharing a sentence is not in itself a finding about the gene and the disease.
acromegaly (continued). "Considering the clinical presentation, acromegaly was suspected and the IGF1 level was found to be significantly increased." (PMID 24616756, 2013). "Among acromegaly patients with a microadenoma, surgery is more than 80 % effective at lowering GH and normalizing IGF-1." (PMID 23054327, 2013). "Acromegaly treatments aim to reduce or control tumor growth, decrease GH levels, and normalize insulin-like growth factor 1 (IGF-1) concentrations, a hormone stimulated by GH production." (PMID 23054327, 2013). "Surgical therapy of acromegaly aims for elimination of the tumour and normalisation of both, growth hormone (GH) secretion and Insulin-like growth factor-1 (IGF-1) concentration." (PMID 22550484, 2012). "Several studies concerning long term follow-up of acromegalic patients demonstrated a link between acromegaly and cancer since IGF1 increase proliferative activity of cells." (PMID 22891085, 2012). "The growth hormone (GH) receptor antagonist pegvisomant is effective in the control of acromegaly since it decreases serum insulin-like growth factor 1 (IGF-1) and improves the health status of people with acromegaly." (PMID 22233881, 2012). "While the goal treatment of acromegaly is the restoration of a normal pulsatile GH secretion pattern and normalization of serum IGF-1, the actual definition of hormonal is ever-changing." (PMID 22518121, 2012). "Remission or “cure” of acromegaly is defined based on two criteria: a normal IGF-1 level adjusted for age and gender and a random GH level <1.0 ng/mL (using an ultrasensitive assay)." (PMID 23209463, 2012). "In retrospective analyses of long-term outcome in acromegaly a normal IGF-1 concentration correlated positively with a normal survival of the patients." (PMID 22550484, 2012). "The IGF-1 concentration was elevated in all patients, but signs and symptoms of acromegaly were subtle in three patients." (PMID 22550484, 2012). "The goals of treatment for acromegaly are to reduce GH levels to <2.5 ng/ml, normalize IGF-1 levels, and/or control tumor mass." (PMID 20211008, 2010). "Our patient had evidently suffered from uncontrolled acromegaly for several years with elevated GH and IGF-1 levels." (PMID 20864785, 2010). "The IGF-1 level of 1006 ng/mL along with the unsuppressed GH confirmed the previous diagnosis of acromegaly." (PMID 20864785, 2010). "The three classes of medical therapy for acromegaly are based on receptor targets of the GH/IGF-1 axis: pituitary somatostatin receptor subtypes, pituitary dopamine D2 receptors, and peripheral GH receptors." (PMID 20478050, 2010). "Therapeutic goals in acromegaly are to reduce and/or stabilize tumor size, control plasma GH and IGF-1 levels (fasting GH levels <2.5 μg/L and IGF-1 levels within the normal range), preserve pituitary function and prevent recurrences." (PMID 20478050, 2010). "We stress the need for close follow-up of patients with acromegaly with adequate control of GH and IGF-1 levels." (PMID 20864785, 2010). "Results from a Phase II study show that pasireotide effectively controls GH and IGF-1 levels in patients with de novo or persistent/recurrent acromegaly, and significantly reduces pituitary tumor volume." (PMID 20478050, 2010). "Prolonged exposure to elevated endogenous levels of GH and/or IGF-1 in acromegaly results in excessive somatic growth and metabolic dysfunction leading to both direct and indirect tissue damage, secondary systemic illness and reduced life expectancy." (PMID 19814797, 2009). "The most widely accepted guidelines for a remission in acromegaly consist of a GH level less than 1 ng/ml in response to a glucose challenge and a normal serum IGF-1 when matched for age and gender." (PMID 19284583, 2009).
acromegaly (continued). "Previous studies have shown that compared with acromegaly patients whose IGF-1 level is 1 × ULN, those with active acromegaly and IGF-1 level of 2.2 ± 1.1 × ULN exhibit more significant cardiovascular structural abnormalities (e.g., vascular endothelial dysfunction)." (PMID 41488995, 2026). "The available data on the effects of fasting and different macronutrients on the GH/IGF-1 axis may be used to develop a tailored diet for patients with acromegaly." (PMID 41472889, 2026). "The regression of symptoms of acromegaly and the normalization of IGF-1 levels following thyroidectomy support the hypothesis of treatment-tumor infarction rather than spontaneous shrinkage." (PMID 41358366, 2026). "Normal GH levels alongside elevated IGF-1 highlight the importance of considering nonpituitary causes of acromegaly, especially in atypical cases." (PMID 41497147, 2026). "Serum IGF-1 decreased after 5 days in the acromegaly patients and after 4 days in controls." (PMID 41472889, 2026). "An imbalance in the conversion of proBDNF to BDNF can significantly affect cognitive function and accelerate the progression of neurodegenerative diseases, but its relevance in the setting of chronic GH/IGF‐1 excess and cognitive impairment in acromegaly remains largely unexplored." (PMID 41550023, 2026). "By day 6, IGF-1 dropped to 65% of baseline in the acromegaly patients and 50% in controls." (PMID 41472889, 2026). "It was worth noting that both GWW and GWE were significantly correlated with 1.5 × ULN IGF-1, which may be due to the variability of the assay and the fact that some acromegaly patients included in this experiment were treated after comprehensive treatment." (PMID 41488995, 2026). "Non-pituitary causes of acromegaly should be considered in elderly patients with atypical biochemical profiles, as hepatic malignancy can rarely produce paraneoplastic IGF-1 excess even in the presence of incidental pituitary lesions." (PMID 41497147, 2026). "Following urgent thyroidectomy, the patient experienced clinical and biochemical improvement with the regression of symptoms of acromegaly, the normalization of IGF-1 levels and the radiological shrinkage of the adenoma, without the need for neurosurgical intervention." (PMID 41358366, 2026). "Background/Objectives: Acromegaly is a systemic connective tissue disease driven by chronic growth hormone (GH) and insulin-like growth factor-1 (IGF-1) excess; yet, the female reproductive tract-especially the extracellular matrix (ECM)-rich cervix-has been poorly studied." (PMID 41897689, 2026). "A third contributing factor may be elevated levels of thyroid hormones, which enhance GH/IGF-1 secretion and metabolic activity, potentially exacerbating acromegaly severity, with resolution following thyroidectomy supporting this hypothesis." (PMID 41358366, 2026). "If acromegaly is suspected, insulin-like growth factor 1 (IGF-1) levels should be measured." (PMID 40452043, 2025). "In addition, in Phase III trials, pasireotide has demonstrated sustained inhibition of GH and IGF-1 in patients with active acromegaly for up to 25 months." (PMID 41287839, 2025). "Therefore, the objective of our pilot study was to determine if patients with acromegaly and modest IGF1 elevations (IGF1 levels 1 to 1.3x ULN) would benefit from stricter normalization of IGF1 with addition or dose escalation of PEGV therapy." (PMID 39959623, 2025). "The patient has complete resolution of his acromegaly, IGF-1 plummeted." (PMID 41287839, 2025). "For example, cortisol deficiency in Addison’s may trigger compensatory pituitary changes, while excess GH and IGF-1 in acromegaly can dysregulate adrenal function, exacerbating hormonal imbalances." (PMID 40842744, 2025).
acromegaly (continued). "Later, a meta-analysis including 160 patients with acromegaly treated with cabergoline as monotherapy reported that 34% of them achieved normal IGF-1 levels (mean cabergoline dose was 2.6 mg/week), and hormonal remission was predicted by lower IGF-1 levels and high PRL levels at baseline." (PMID 40590355, 2025). "Considering this potentially paradoxical impact, we aimed to determine whether MASLD was more prevalent in acromegaly patients, assess the risk of hepatic fibrosis, and clarify the uncertain relationship between MASLD and GH/IGF-1 levels." (PMID 40725515, 2025). "When the adenoma arises from somatotroph cells, it may lead to GH hypersecretion, resulting in elevated IGF-1 levels and the clinical syndromes of acromegaly in adults or gigantism in children." (PMID 41458762, 2025). "In acromegaly, the increased occurrence of macroglossia may be explained by sustained elevations in GH and IGF-1." (PMID 41353330, 2025). "In acromegaly, patients secrete GH in excess, leading to significantly increased IGF-1 levels." (PMID 40141202, 2025). "Surgical intervention successfully alleviated acromegaly symptoms and normalized IGF-1 levels." (PMID 40523964, 2025). "This case raises the question of whether cardiac morphological changes occur in patients with acromegaly who have GH and insulin-like growth factor-1 (IGF-1) levels well controlled." (PMID 40697972, 2025). "In patients with acromegaly, GH and IGF-1 concentrations are elevated." (PMID 40149581, 2025). "Given that the patient was suffering from more pressing issues in the ICU, we hypothesized that she had undiagnosed acromegaly based on the MRI findings, as well as the IGF-1 and IGFBP-3 values." (PMID 41589173, 2025). "In acromegaly, chronic GH excess and elevated IGF-1 levels may influence local inflammatory processes, angiogenesis, and bone regeneration, which are key elements for successful osseointegration." (PMID 41295066, 2025). "Collectively, the high expression of GIPR in PIT1/SF1 tumors may account for higher IGF-1 levels than in PIT1 tumors in acromegaly." (PMID 40421250, 2025). "The high prevalence of valvulopathy in acromegaly can be explained by its late diagnosis, the long evolution of the disease, having active disease, and continued exposure to high concentrations of GH and IGF-1." (PMID 40149581, 2025). "Chronic GH and IGF-1 exposure in acromegaly affects both myocardial structure and function." (PMID 40142714, 2025). "However, when specifically analyzing patients with acromegaly, we found that disease activity (IGF-1 levels) and left ventricular remodeling (LV diameter) were independent predictors of impaired GLS, whereas BMI did not emerge as a significant predictor." (PMID 41307388, 2025). "Her IGF-1 levels were normalised, with resolution of all signs of active acromegaly." (PMID 41287839, 2025). "Indeed, higher IGF-1 levels at diagnosis can predict the development of GMAs in acromegaly patients, and GH-Par patients typically have higher IGF-1 levels compared to GH-NPar patients." (PMID 39841390, 2025). "Acromegaly is a rare condition, with over 95% of cases attributed to pituitary adenoma (PA) secreting growth hormone (GH), leading to excessive levels of GH and insulin-like growth factor-1 (IGF-1) secretion." (PMID 39707075, 2025). "Cimdelirsen was evaluated in a 4-month double-blind, placebo-controlled phase 2 study in uncontrolled acromegaly patients (IGF-1 between 1.3 to 5 x upper limit of normal) treated with long-acting somatostatin receptor ligands (NCT03548415) and in an open-label extension safety study (NCT03967249)." (PMID 39944202, 2025). "Elevated insulin-like growth factor 1 (IGF-1) confirmed the diagnosis of acromegaly." (PMID 39990019, 2025). "Acromegaly is a rare chronic disorder characterized by excessive growth hormone (GH) secretion, most commonly due to a pituitary adenoma, which results in elevated circulating insulin-like growth factor-1 (IGF-1) levels." (PMID 41293738, 2025).
acromegaly (continued). "Hence, conventional acromegaly treatment outcomes have focused on biochemical and radiological criteria, such as improvements in IGF1, GH, and pituitary tumor size." (PMID 39959623, 2025). "Postsurgical diuresis may occur due to a decrease in GH and IGF‐1 levels, and even in patients with complete resolution of acromegaly, it may take several months for IGF‐1 levels to return to normal." (PMID 40546879, 2025). "Nowadays, radiation therapy is regarded as an efficient adjuvant approach in acromegaly treatment and is mainly being used in patients who cannot control the GH and insulin-like growth factor-1 properly or develop tumor growth, even with surgery or medications." (PMID 41334063, 2025). "In a cross-over study of acromegaly patients inadequately controlled on octreotide 30 mg, pasireotide was more effective in controlling parameters of acromegaly activity (GH < 2.5 μg/L, normal IGF-1)." (PMID 41287839, 2025). "Independent associations between acromegaly and the development of malignancies have been described, attributed to the mitogenic effects of growth hormone and insulin-like growth factor 1,8 but never in relation to a genetic syndrome such as FAP." (PMID 41467151, 2025). "However, no consensus was reached on some statements on the definition of acromegaly under control when IGF-1 and GH levels show different responses to therapies (statements 2.5 and 2.6)." (PMID 38809458, 2024). "In addition, an oral glucose tolerance test should be considered in individuals with tall stature who have IGF-1 level above RI to diagnose acromegaly." (PMID 39403490, 2024). "Moreover, studies have shown a direct relationship between the development of goiter and GH and IGF-1 levels or the duration of acromegaly." (PMID 38455769, 2024). "Additionally, in acromegaly patients with controlled disease, GH levels were higher in postmenopausal females than males, while IGF-1 levels were comparable." (PMID 39104813, 2024). "Also, a positive correlation exists between GH/IGF-1 levels and fibrinogen levels in active acromegaly." (PMID 37584889, 2024). "Acromegaly is an example of a disease characterized by an increased concentration of GH and IGF-1." (PMID 38668933, 2024). "Nonetheless, elevated levels of GH and IGF-1, which are significant hormonal features of acromegaly, may have distinct roles in the development of TC in this population." (PMID 39104813, 2024). "If acromegaly is suspected, IGF-1 levels should be screened." (PMID 39598257, 2024). "In contrast to these studies indicating a stimulatory effect of the GH/IGF-1 axis on irisin levels, another study in 43 adults with acromegaly, most of whom were controlled, observed that irisin levels were lower in adults with acromegaly than in the controls." (PMID 38405219, 2024). "In support of this hypothesis, high circulating GIP levels in acromegaly may be due to increased IGF-1 levels, which induce GIP synthesis in the intestinal neuroendocrine cell line STC-1." (PMID 37344722, 2024). "The impact of GH/IGF-1 levels on skeletal muscle in acromegaly is still controversial." (PMID 38967765, 2024). "Background/Objectives: Acromegaly-induced prolonged exposure to growth hormone and insulin-like growth factor 1 may have significant cardiovascular effects." (PMID 39337121, 2024). "Octreotide exerts its effect by inhibiting the release of pituitary and gastroenteropancreatic hormones, i.e., serum growth hormone (GH) and insulin-like growth factor 1/somatomedin C (IGF-1), which are hyperexcreted in GH-releasing hormone-secreting adenoma promoting acromegaly." (PMID 39861670, 2024). "This could account for the predominance of GH diabetogenic effects over IGF-1 insulin-sensitizing effects in acromegaly patients." (PMID 39331882, 2024).
acromegaly (continued). "This meta-analysis aimed to provide a comprehensive evaluation of IGF-1 levels in different populations, including the general population, HF patients, and individuals with treatment-naïve acromegaly, a condition characterized by excessive GH secretion and elevated IGF-1 levels." (PMID 39544311, 2024). "In the case of effective treatment of acromegaly, including surgery for pituitary adenoma and normalisation of GH and IGF-1 levels, myocardial function may normalise even in the case of severe fibrosis." (PMID 39598257, 2024). "Few studies have investigated IGF-1 status in patients with acromegaly and bronchiectasis." (PMID 39220366, 2024). "Furthermore, studies of patients with Acromegaly, all of whom displayed elevated levels of circulating IGF1, have poor quality of health and life in old age." (PMID 39245994, 2024). "Patients with normal IGF-1 levels are usually considered acromegaly unlikely." (PMID 39044175, 2024). "Acromegaly, a rare endocrine disorder typically resulting from a pituitary adenoma, is marked by the continuous overproduction of growth hormone (GH) and insulin-like growth factor-1 (IGF-1)." (PMID 39331882, 2024). "Moreover, it is often difficult to establish the precise time when acromegaly started, so it is difficult to assess the levels of GH and IGF-1 to which the patient was exposed during the evolution of the disease." (PMID 39329880, 2024). "Acromegaly disease activity was classified according to the IGF-1 index (normal value < 1.0)." (PMID 38244140, 2024). "Acromegaly (AC), which involves prolonged exposure to growth hormone (GH) and insulin-like growth factor 1 (IGF-1), may have significant cardiovascular effects, including hemodynamic dysfunction of the heart and blood vessels." (PMID 39337121, 2024). "The mechanisms leading to OP in the background of acromegaly consist of higher GH and IGF-1 levels." (PMID 39595124, 2024). "However, the glucose tolerance test result was suitable to determine acromegaly for the patient to be included in the rare incurable disease registry, so the patients included in this study were those with high serum IGF-1 level." (PMID 39220366, 2024). "Furthermore, significantly higher IGF-1 concentrations were shown in patients with acromegaly in comparison with CG for both classification I (AA+CTA+CA, CG; p<0.001) and classification II (AA, CTA+CA, CG; p<0.001)." (PMID 39741885, 2024). "Conversely, managing IGF-1 levels in individuals with acromegaly could be crucial for preventing cardiac complications." (PMID 39544311, 2024). "GH-Par, common in acromegaly and associated with an increased prevalence of glucose metabolism abnormalities, is found also in a subset of non-acromegalic subjects with high IGF-1 levels, suggesting its possible involvement in the early phase of the disease." (PMID 37344722, 2024). "For example, acromegaly, which is characterized by excessive growth hormone (GH) and IGF-1, leads to abnormal bone remodeling and disproportionate bone growth, with thickened cortical bone and thin trabeculae, which paradoxically weakens the overall bone strength." (PMID 39200996, 2024). "Furthermore, they showed that exosomal hsa-miR-21-5p plays an important role in this process (which is distinct from that of the GH/IGF-1 axis), providing a novel mechanism for acromegaly development." (PMID 36875488, 2023). "Nevertheless, a meta-analysis focused on the response to cabergoline in acromegaly showed that this response is dependent on the IGF1 baseline levels, with greater chances to achieve IGF-1 level normalization with lower basal IGF-1 levels, regardless of the presence or absence of hyperprolactinemia." (PMID 37762304, 2023). "Patients with acromegaly have chronically high levels of GH and IGF-1." (PMID 38032888, 2023).